CXCL10 (C-X-C motif chemokine ligand 10)
Diseases named in the same sentence as CXCL10 in open-access papers (continued):
Sharing a sentence is not in itself a finding about the gene and the disease.
breast carcinoma (176 papers, 2011 to 2026). "The FBXO24-mediated depletion of LSD1 led to increased expression of CCL5 and CXCL10 in breast cancer cells, which was associated with increased level of H3K4me2 in the promoter regions of their genes." (PMID 40940894, 2025). "In the context of HER2-positive breast cancer, CXCL10 emerges as being particularly significant, implicated in trastuzumab responses through interferon-gamma-inducible protein 16 (IFI16)-dependent STING signaling." (PMID 39682150, 2024). "We have identified that the underlying biology of the DDIR signalling in GOA, similar to breast cancer, is associated with constitutive gene up-regulation of the chemokines CXCL10 and CCL5 and an inflamed TME." (PMID 38744099, 2024). "Expression of CXCL10 in breast cancer can enhance tumour-specific T cell infiltration, and is associated with increased overall patient survival; similarly, the delivery of CXCL10-loaded nanoparticles inhibits the growth of liver tumours." (PMID 34200333, 2021). "Contrary to exhibiting anti-tumour actions and attenuating angiogenesis, CXCL10 also has tumour-promoting ability and has been associated with advanced human cancers, in particularly in breast cancer progression and metastasis, but also in PDAC." (PMID 31415645, 2019). "We could show that CXCL10 is strongly associated with SIGLEC1 expression in breast cancer specimens in primary tumors using the TCGA database in R2 (r2.amc.nl) (R=0.630, P=2.07e-122)." (PMID 37404831, 2023). "Previous studies have shown that CXCL10 is a potential tumor biomarker of malignant diseases which not only has diagnostic value but also has prognostic value for tumors, such as hepatocellular carcinoma, colorectal cancer, and breast cancer." (PMID 36207693, 2022). "Importantly the CXCL10/CXCR3 axis is activated in BRCA-mutant breast cancer and has been implicated in breast cancer progression and metastasis in both in vivo and clinical studies." (PMID 31320901, 2019). "By contrast, two described properties of CXCL10 may underlie its potential tumor-promoting effects: One is its direct action on the proliferation of breast cancer cells." (PMID 24725474, 2014). "By transcriptomic profiling, we observed high expression of Cxcl10 in dormant cells in two different orthotopic, syngeneic models of breast cancer dormancy (D2.0R and 4T1-MR20)." (PMID 41617729, 2026). "This was associated with enhanced production of chemokines (CCL5, CXCL10, CXCL11, IL-15) and increased CD8+ T cell infiltration, causing Granzyme B-mediated induction of breast cancer cell apoptosis." (PMID 40940894, 2025). "For example, high CXCL10 levels were associated with CD4+ and CD8+ T cell infiltration in the TME in breast cancer, but in CRC and NSCLC high CXCL10 levels were associated with shorter survival." (PMID 40589738, 2025). "We conclude that decreased expression of CXCL9 (and potentially CXCL10) is associated with worse patient outcome and downregulation of CXCL9/10 with age is a feature of human HER2+ breast cancers." (PMID 41332581, 2025). "CXCL9, CXCL10, and CXCL11 have tumor-promoting abilities and have been associated with advanced human cancer, particularly in elderly breast cancer patients' progression and metastasis." (PMID 40584290, 2025). "For instance, in breast cancer, flavonoid drugs like apigenin have been confirmed to inhibit NF‐κB‐dependent production of CXCL10 in tumor cells, thereby reducing proliferation of precancerous epithelial cells and invasiveness of human breast cancer cells." (PMID 41427020, 2025). "The upregulation of CXCL10 is particularly significant, as studies have identified that CXCL10 overexpression serves as a marker of favorable prognosis in breast cancer." (PMID 40805064, 2025). "Simultaneously, the differentially expressed genes related to breast cancer, such as FHL1, GPM6B, RELN, and CXCL10 were discovered between the two risk groups." (PMID 38748500, 2024).
breast carcinoma (continued). "Biologically, the DDIR effect in GOA, similar to breast cancer, appears to be driven by the chemokines CXCL10 and CCL5, the pro-inflammatory functions of which include T-cell recruitment and expansion." (PMID 38744099, 2024). "Serum CXCL10 levels are increased in breast cancer patients compared to healthy controls and are related to endocrine therapy resistance in vitro." (PMID 38594742, 2024). "This suggests that neurons in the TME of breast cancer are able to promote tumor cell migration by releasing CXCL10 or CXCL12 and combining with CXCR3." (PMID 39429695, 2024). "In summary, the CXCL10/CXCR3/Akt pathway plays an important role in relieving breast cancer pain both in the early stage by inhibiting nerve metastasis and in the late stage of metastasis." (PMID 39429695, 2024). "We found that DSF/Cu up-regulated the expression of CXCL10, CCL5 and IFN-β in multiple high metastatic breast cancer cell lines, which was associated with the activation of the STING-TBK1-IRF3 pathway." (PMID 38370371, 2024). "Although ROC curve analysis for Gln, Nrf2 and CXCL10 suggests their potential as breast cancer biomarkers for diagnostics in FF, further studies with large sample size must be conducted to understand the relevance of these species." (PMID 36984881, 2023). "Meanwhile CXCL10 facilitates the tamoxifen resistance of breast cancer cells to enable the prognosis of breast carcinoma via the AKT pathway." (PMID 37484915, 2023). "Downregulation of interferon-γ inducible protein 16 (IFI16), a direct target of EZH2, decreases stimulator of interferon genes (STING) activation and downstream CXCL10/11 expression in response to trastuzumab treatment in HER2+ breast cancer (BC)." (PMID 37198402, 2023). "CXCL10 increases the proliferation of mouse breast cancer stem cells and breast cancer cells, and is significantly associated with triple negative breast cancer versus HER2+, Luminal A and Luminal B breast cancer." (PMID 36608258, 2023). "High levels of CCL5 and CXCL10 in breast cancer correlate with advanced stages of the disease and reduced survival of metastatic breast cancer patients, respectively." (PMID 36949770, 2023). "Only changes in five analytes (CXCL5, CXCL1, CCL17, CXCL10, and IL-6) were seen to overlap across all four breast cancer cell-line EV-stimulated conditions." (PMID 37441083, 2023). "We found that the mRNAs of the pro-inflammatory molecules Cxcl10 and IL-6 were upregulated in both cell types, while TNFα mRNA was upregulated only in mammary carcinoma cells when cells were transfected with poly(I:C)." (PMID 35737804, 2022). "Specifically, we found that miR-155 overexpression in human primary breast cancer cells significantly increased Ccl5 and Cxcl10/11 expression." (PMID 35925680, 2022). "Except CXCL10, high expression levels of CCL5, CCL19 and CXCL9 were significantly associated with better prognosis in breast cancer patients." (PMID 35359417, 2022). "The overexpression of circulating CXCL10 was detected in some of human cancers, such as breast cancer and colorectal cancer." (PMID 36207693, 2022). "The ranges of the circulating CXCL10 detected in other study on breast cancer were different from the values in our study." (PMID 36207693, 2022). "Tumoral IP-10 (CXCL10) has been correlated with tumor stage and lymphoid metastasis in women with breast cancer, with higher levels indicating poorer prognosis." (PMID 35681702, 2022). "Some researchers have found that the CXCL10 can be a poor prognostic indicator of renal cancer and breast cancer." (PMID 35083488, 2022). "Our study showed increased proliferation and migration of both MCF-7 and MDA-MB-231 breast cancer cell lines with an increased dose of exogenous CXCL10." (PMID 34504204, 2021). "We evaluated the effect of CXCL10 on tumor cell proliferation and migration using breast cancer cell lines MCF-7 and MDA-MB-231." (PMID 34504204, 2021).
breast carcinoma (continued). "Subsequently, the educated CAFs then secrete CXCL9/CXCL10 to stimulate CXCR3 on breast cancer cells, thereby maintaining the cancer stemness of breast cancer cells to promote lung metastatic colonization." (PMID 33407730, 2021). "While the exact functions of CXCL10 on FOXP3+ Tregs in breast cancer remain yet to be elucidated, it can be concluded that CXCL10 expression is associated with FOXP3+TIL infiltration in both DCIS and invasive carcinoma." (PMID 34504204, 2021). "The results showed that the expression level of CXCL10 was upregulated in most solid tumors, including bladder cancer, breast cancer, colorectal cancer, head and neck cancer, and liver cancer." (PMID 34276760, 2021). "Our investigations identified a possible role for one CXCR3 ligand in particular, IP-10 (CXCL10), in driving the growth of metastatic breast cancer cells." (PMID 34123844, 2021). "Has_circ_0000515 can sponge miR-326 to promote cervical cancer progression by releasing ELK1 transcription and regulate the miR-296-5p/CXCL10 signalling pathway axis to induce the pathogenesis of breast cancer." (PMID 35155186, 2021). "Of the CXCR3 ligands, IP-10 (CXCL10) was the most abundant, correlated significantly with shortened survival of human breast cancer patients with metastatic disease and was highest in those with triple negative (TNBC) disease." (PMID 34123844, 2021). "The expression of CXCL10 was positively correlated with immune scores in breast cancer patients (Spearman's rank correlation coefficient, R > 0.6, P ≈ 0)." (PMID 34158843, 2021). "CXCL10 was significantly expressed at high levels in 16 unique analyses in breast cancer and 16 unique analyses in lymphoma." (PMID 34439306, 2021). "CXCL10 has a leading role in modulating cellular migration in the mouse breast cancer cell line 4T154." (PMID 32728097, 2020). "CXCL10 plays indispensable role in breast cancer patients for immune checkpoint-based therapies, while CXCL1 had been shown to be involved in resistance to cancer chemotherapies." (PMID 32963527, 2020). "TNFAIP3 was strongly associated with the infiltration of all types of immune cells in breast cancer, and CXCL10 and IFNG behaved similarly in all immune cell types except macrophages." (PMID 33102239, 2020). "Once secreted from fibroblasts, CXCL9 and CXCL10 bind to CXCR3 on the surface of a subpopulation of breast cancer cells to complete a paracrine loop that promotes initiation and growth of metastasis in the lungs." (PMID 32198421, 2020). "As an example, CXCL10 is proposed to have both pro- and anti-proliferative action on breast cancer depending on the receptors it engages." (PMID 32956403, 2020). "Accordingly, treatment with an antibody of CXCL10 reduces bone marrow colonization of breast cancer cells." (PMID 33123472, 2020). "These experiments confirm that IL-1α/β are indeed the factors contained within CM from metastatic breast cancer cells that drive CXCL10 expression in lung fibroblasts via IL-1R." (PMID 32198421, 2020). "CXCL10 is another chemokine produced in the BMAs that motivates the directional movement of breast cancer cells by its receptor CXCR3 on cancer cells." (PMID 33123472, 2020). "This pro-tumoral CXCL10 feed-forward loop was also observed in breast cancer; albeit, CXCL10 also attracted more CD4+ and CD8+ lymphocytes to the TME, in a paracrine manner, which attenuated tumor progression." (PMID 31216755, 2019). "The CX3CR1/CX3CL1 and CXCR3/CXCL10 axes have been demonstrated to be involved in the proliferation, survival, and metastasis of various malignant tumor types, including breast cancer, and were suggested to predict the site of metastatic relapse." (PMID 31026363, 2019). "In breast cancer, Ras-induced CXCL10 overexpression contributes to the development of breast tumours, and overexpression of CXCR3 is associated with poorer overall survival." (PMID 31308057, 2019).
breast carcinoma (continued). "It has been reported that both CXCR3 and its ligand CXCL10 are highly upregulated in breast cancer cells." (PMID 30177620, 2018). "CXCL10 was initially thought to be a chemoattractant for T cells; however, more recently its role in breast cancer is thought to be more complex." (PMID 28603578, 2017). "For example, unfractionated heparin inhibits IFN-γ-induced CXCL9 and CXCL10 production by human breast cancer cells dose-dependently." (PMID 29379506, 2017). "A CXCR3-CXCL10 autocrine loop has previously been found in breast cancer cell lines in vitro, where CXCL10 is secreted by the cancer cells." (PMID 25798946, 2015). "In addition, we found the up-regulation of genes as the chemokine CXCL10, involved in immune and inflammatory processes and that posses anti-angiogenic activity, which are associated with increased immune infiltration and improved survival in patients with solid malignancies including breast cancer." (PMID 24946763, 2014). "COX-2 inhibition increases release of CXCL9 and CXCL10 proteins from breast cancer cells and induces IL-8 down-regulation." (PMID 23405235, 2013). "We now demonstrate that PGE2 inhibits IFN-γ induced CXCL9 and CXCL10 secretion from breast cancer cells and that, conversely, the COX inhibitors acetylsalicylic acid (ASA) and indomethacin augment this release." (PMID 22333315, 2012). "For example, elevated expression of CXCL10 and its receptor CXCR3 has been associated with breast cancer metastasis." (PMID 23056468, 2012). "Suppressing endogenous PGE2 synthesis by cyclooxygenase inhibition increases CXCL9 and CXCL10 release from breast cancer cells and is therefore a pharmacologic candidate to enhance intratumoral immune infiltration." (PMID 22333315, 2012). "Our results demonstrate that PGE2 inhibits, whereas COX inhibitors induce the release of CXCL9 and CXCL10 from breast cancer cells." (PMID 22333315, 2012). "In this study, we have identified the COX pathway as a potential pharmacologic candidate to enhance the intratumoral accumulation of CXCL9 and CXCL10 levels in breast cancer." (PMID 22333315, 2012). "In estrogen receptor–positive (ER+) breast cancer, a notable example is circTNK2, which has been therapeutically targeted using nanoparticles co-loaded with antisense oligonucleotides (ASOs) and immunomodulatory CXCL10 plasmids." (PMID 41438756, 2025). "Although research on W6134 and XY018 in diverse breast cancers is growing, significant gaps remain in understanding their roles in canine mammary cancer cells and how they influence the key inflammatory gene expression such as CXCL10 and MECOM." (PMID 40805064, 2025). "Additionally, developmental trajectories of CXCL10+ cDCs and monocytes in different breast cancer subtypes were analyzed." (PMID 39104420, 2024). "In summary, the deficiency in GSDMD did not exert an impact on tumor growth, immune cell infiltration, or the immune landscape in either the EO771 breast cancer or the Hepa1-6 hepatoma model, although intratumoral Cxcl10 levels were elevated in Hepa1-6 tumors grown in Gsdmd-/- mice." (PMID 39224600, 2024). "Increased levels of CCL7, CXCL9, and CXCL10 were found in the plasma of breast cancer patients." (PMID 39684443, 2024). "Next, we investigated the developmental origins of CXCL10+ cDCs in breast cancer." (PMID 39104420, 2024). "Moreover, chemokines have a multifaceted role in tumor generating an immunosuppressive tumor microenvironment, including breast cancer in which chemokine CXCL10 contributes to the progression of ductal carcinoma in situ to invasive carcinoma of the breast." (PMID 36984881, 2023). "The increased release of uPA, suPAR, and CXCL10 immunomodulatory factors by D-treated breast cancer cell lines observed here, might be related to a similar mechanism." (PMID 37957750, 2023).
breast carcinoma (continued). "Interestingly, the expression of CXCL10 have strong prognostic value for disease-free survival in the breast cancer human cohort, suggesting a critical contribution of this molecule in breast cancer outcomes." (PMID 35960749, 2022). "Similarly, overexpressed CXCL10 has been also documented in breast cancer, which can facilitate cell invasion, migration and colony formation." (PMID 33926524, 2021). "In order to determine whether exogenous CXCL10 treatment promotes breast cancer cell proliferation, we added CXCL10 to MCF-7 and MDA-MB-231 cell lines at a concentration of 20 ng/ml, 40 ng/ml, 60 ng/ml, 80 ng/ml, and 100 ng/ml, respectively." (PMID 34504204, 2021). "Next, we performed Western blot analysis to validate that CXCL10 does induce EMT in breast cancer." (PMID 34504204, 2021). "Effect of CXCL10 on breast cancer cell proliferation and invasion was examined in vitro, and expression of CXCL10 and its relationship with immune cell infiltration was assessed in breast cancer samples." (PMID 34504204, 2021). "Examples of diseases that can reliably be diagnosed through salivary analysis are pancreatic (miR-3679-5p and miR-940), lung (cytokines IL1RN, IL1B, CXCL10), and breast cancers (phenylalanine, tryptophan), as well as myocardial infarction (C-reactive protein, myoglobin, and myeloperoxidase)." (PMID 32019170, 2020). "Indeed, both CXCL9 and CXCL10 promoted sphere formation and lung colonization by breast cancer cells." (PMID 32198421, 2020). "Importantly, expression of CXCL9 and CXCL10 correlated markedly in dissected distant metastases samples from breast cancer patients, indicating co-expression of these cytokines in human metastasis." (PMID 32198421, 2020). "Interestingly, CXCL-1 and CXCL-10 were unaltered in breast cancers whereas significant increased levels were detected in dense breast tissue." (PMID 29387062, 2017). "IP-10 (chemokine CXCL10) is an important mediator in bidirectional MSCs/breast cancer signaling." (PMID 24209831, 2013). "PGE2 inhibits IFN-γ-induced release of CXCL9 and CXCL10 in human breast cancer cells." (PMID 22333315, 2012). "Subsequently we tested whether the COX-2 specific inhibitor celecoxib would also raise CXCL9 or CXCL10 release from MCF-7 or MDA-MB 231 breast cancer cells." (PMID 22333315, 2012). "Moreover, the correlation of CXCL10 with immune checkpoint blockade (ICB)-related genes has been reported not only in breast cancer but also consistently across 32 other malignancies, including DLBCL, highlighting its broad involvement in tumor immune regulation." (PMID 41476984, 2025). "In MDA-MB-435 and MCF-7 breast cancer cells, CXCR3 and CXCL10 are upregulated via the Ras signaling pathway, which contributes to breast cancer development, suggesting that CXCL10-CXCR3 autocrine function may play an essential role in breast cancer motility and metastasis." (PMID 30177620, 2018). "Similarly, under hypoxia, MSCs promote breast cancer metastasis through CXCR3/CXCL10 interaction." (PMID 25110692, 2014). "CXCL10 and its receptor CXCR3 play a crucial role in breast cancer bone metastasis and osteoclast activation." (PMID 40786052, 2025). "For instance, in breast cancer patients, elevated serum levels of CXCL9 and CXCL10 are observed compared to healthy controls, and high levels of CXCL9 transcripts have been linked to better outcomes." (PMID 40362215, 2025). "Trastuzumab-induced NK cell activation against SKBR3, BT474 and HC1954 HER2-positive breast cancer cells resulted in the secretion of CCL5, IFN-γ and the consequent production of CXCL9 and CXCL10, as analysed by ELISA in cell-free coculture supernatants." (PMID 38167224, 2024). "A positive correlation has been found between increased CXCL10 expression and improved prognosis in various human cancers, including CRC, esophageal squamous cell carcinoma, hepatocellular carcinoma and breast cancer." (PMID 39443817, 2024).